BRAF (B-Raf proto-oncogene, serine/threonine kinase)
Diseases named in the same sentence as BRAF in open-access papers (continued):
Sharing a sentence is not in itself a finding about the gene and the disease.
melanoma (continued). "The COMBI-AD trial also reported a similar RFS benefit with dabrafenib plus trametinib versus placebo in patients with BRAF-mutant melanoma." (PMID 36058945, 2022). "Increasing evidence has been reported for the synergistic and additive effects of the joint use of HDAC inhibitors and BRAF inhibitors in colon cancer and melanoma." (PMID 35936102, 2022). "Both BRAF(V600E) inhibitors are approved for use in combination with a MEK inhibitor for treatment of advanced melanoma and demonstrate an example of a successful vertical pathway inhibitor combination." (PMID 34958800, 2022). "The RAS inhibitor rigosertib has been shown to block AKT activation and synergize with anti-PD-1/anti-CTLA-4 in B16F10 (NRASWTBRAFWT) and YUMM3.3 (BRAF-mutant) melanoma preclinical models." (PMID 35806358, 2022). "We retrospectively reviewed charts of patients with BRAF-mutant melanoma with metastasis to the brain with at least one untreated brain metastasis at the time of initiation of BRAF plus MEK inhibitors at our institution from 2006 to 2020." (PMID 36579260, 2022). "Despite the fact that c-KIT mutation occurred at a lower incidence than BRAF and NRAS genes in most of the melanoma patients, it represented 36% of acral lentiginous melanomas in cutaneous melanoma." (PMID 35720122, 2022). "The lncRNA SAMMSON, which controls mitochondrial metabolism and functions as an oncogene in melanoma, is upregulated following inhibition of the ERK signaling in mutant BRAF melanoma cells, and its depletion sensitizes melanoma cells to BRAF inhibitors." (PMID 35159386, 2022). "Of 40 (36.7%) patients with BRAF V600E/K melanoma, pembrolizumab was prescribed to 18 (45.0%), nivolumab to 16 (40.0%), and dabrafenib/trametinib to three (7.5%) patients." (PMID 35336796, 2022). "The introduction of targeted agents for BRAF-mutant melanoma has significantly improved overall survival in a large proportion of patients." (PMID 36181568, 2022). "Vemurafenib (PLX4032, Plexxikon or RG7204, Roche Pharmaceuticals), a potent inhibitor of BRAF (BRAFi) with high selectivity for BRAF V600E, was the first molecularly targeted therapy licensed for the treatment of advanced melanoma." (PMID 36613518, 2022). "recently reported that BRAF inhibitors promoted pyroptosis in anticancer immune responses, pointing to novel treatment approaches for refractory melanoma." (PMID 36532053, 2022). "We propose the p38-dependent regulation of SOX2 phosphorylation and activity as a mechanism of adaptive response toward BRAF-targeted therapy in melanoma cells." (PMID 35944584, 2022). "It has been proven that following the activation of the NRAS / BRAF pathway in melanoma, genes promoting cell proliferation such as SNAIL2 and ZEB2 are replaced by those regulating the migration such as ZEB1 and TWIST1." (PMID 35820816, 2022). "Supplementation of treated cells with SOD or inhibiting nitric oxide synthase counteracts the effectiveness of BRAF-inhibitor treatment and rescues the growth of BRAF-mutant melanoma cells." (PMID 35326683, 2022). "Moreover, the plasmatic fractions of BRAF mutations measured in the first week following the initiation of immunotherapy might predict the response to PD-1 or CTLA-4 inhibitors in advanced melanomas." (PMID 36295075, 2022). "Actually, BRAF V600 alterations have been identified not only in melanoma, hairy cell leukemia, papillary thyroid cancer, small-cell lung cancer, and colorectal cancer, but also in GBM." (PMID 36358795, 2022). "The effect of MITF repression of these genes was found to be reversible when MITF was knocked down in melanoma cells, resulting in increased focal adhesion complexes and resistance to BRAF inhibitor treatment." (PMID 36119516, 2022). "Our data strengthen a concept for the clinical combination of BRAFi with high-dose ascorbate to target melanoma cells, particularly to counteract acquired resistance to BRAF inhibition, but also to exploit potential additive effects of their combination." (PMID 35406796, 2022).
melanoma (continued). "Studies have indicated that prolonged exposure to BRAF/MEK inhibitors renders melanomas less dependent on glycolysis but addicted to mitochondrial metabolism and anaplerotic pathways, such as glutaminolysis." (PMID 36555289, 2022). "In BRAF-mutated melanomas, RAS-GTP levels are insufficient to promote BRAF dimerization, therefore the inhibition of BRAF monomers is sufficient for ERK inactivation." (PMID 35494017, 2022). "An interesting highlight in this context is vemurafenib, the first clinically‐approved targeted agent for the treatment of BRAF(V600E)‐mutant advanced melanoma." (PMID 36911295, 2022). "In this paper, we evaluated circulating basal levels of 6 previously identified miRNAs in serum samples of 70 BRAF-mutant melanoma patients before starting targeted therapy." (PMID 36438490, 2022). "Here we present a retrospective case series of patients with resected stage III melanoma treated with adjuvant BRAF and MEK inhibition with the purpose of describing toxicities in a real-world population." (PMID 36212431, 2022). "When BRAFi and HSV were tested in combination in vitro in the BRAF V600E mutant murine melanoma 4434, although both agents were cytotoxic when tested alone, no significant combination effect was seen." (PMID 35338089, 2022). "In murine melanoma models of BRAF and NRAS mutant melanoma, high TMB increases MAPK inhibitor response durability in a CD8 + T cell dependent manner." (PMID 36058945, 2022). "Guidelines recommend BRAF V600 and NRAS mutation testing on tumor specimens for resectable or unresectable stage III/IV melanoma." (PMID 35804825, 2022). "In recent years, our laboratory has intensively studied the role of miRNAs in melanoma progression and resistance to BRAF/MEK inhibitors 27, 41-43." (PMID 36438490, 2022). "JUN and/or AP-1 and TEAD has been shown to induce resistance to vemurafenib (small-molecule inhibitor of BRAF V600E) in cultured patient-derived melanoma cells." (PMID 35883668, 2022). "Taken together, these results indicate that DUSP4 selectively controls cell viability in BRAF-mutant melanoma cells by functioning as a rheostat for ERK signaling which in turn drives the PAX3-MITF pathway." (PMID 35580987, 2022). "Approved adjuvant treatment options for stage III melanoma are the immune checkpoint inhibitors (ICI) pembrolizumab and nivolumab, and in presence of a BRAF V600E/K mutation additionally dabrafenib in combination with trametinib (BRAFi/MEKi)." (PMID 35336796, 2022). "Two other B-Raf inhibitors, dabrafenib and encorafenib, were subsequently developed, and currently all three are being used to treat advanced BRAF-mutated melanomas." (PMID 36143375, 2022). "Seventy-five percent of Chinese melanoma patients were found to be targetable, and the predominant druggable gene was BRAF based on DNA-NGS." (PMID 36612279, 2022). "In melanoma cells, DTP-associated transcriptional changes to BRAF inhibitors were partially mediated by transcription factor activity including TEAD32." (PMID 36575215, 2022). "Work done in melanoma cell lines has shown different responses to these inhibitors based on the level of BRAF fusion expression in the cell lines (controlled by the promoter of the 5′ partner) as well as the presence of a dimerization domain in the 5′ partner." (PMID 36503484, 2022). "Treating resistant melanoma cells with IGF1R inhibitors restores their BRAFi sensitivity, and a combination of BRAF/MEK inhibitors with IGF1R inhibitors significantly reduces melanoma cell growth in vitro and in vivo." (PMID 35565444, 2022). "Beyond using BRAF inhibitors singly, the BRAF(V600E/K)-mutant melanoma patients benefited from the combinational treatments of BRAF inhibitor and MEK inhibitor." (PMID 36145516, 2022).
melanoma (continued). "Our study offers a novel examination of a real-world population with resected stage III melanoma treated with adjuvant combination BRAF and MEK inhibition." (PMID 36212431, 2022). "Vemurafenib and dabrafenib, two BRAF inhibitors, have significantly improved response rates (approximately 50%), progression-free survival (PFS) and better OS than chemotherapy in patients with metastatic BRAF V600E/K mutant melanoma." (PMID 35053435, 2022). "Combination IO (anti-CTLA4 and anti-PD-1) and TT that inhibit BRAF V600 E/K and MEK (known to be mutated in approximately 40-50% of melanoma patients) are effective at treating MBM and prolonging PFS." (PMID 35600355, 2022). "We further found that plasma lipid profiles in advanced stage melanoma patients were modulated by BRAF/MAPKi therapy." (PMID 35565240, 2022). "Our data demonstrate for the first time that HDACI (ITF2357 and SAHA) target oncogenic BRAF in melanoma cells." (PMID 36009541, 2022). "Vemurafenib and dabrafenib provide potent selective inhibition of kinase activity in BRAF V600-mutant melanoma by blocking ERK phosphorylation and cellular proliferation." (PMID 35406444, 2022). "The ORR of BRAF inhibitor Vemurafenib in the treatment of BRAFV600E mutant melanoma is up to 50%, which improves the progression-free and overall survival rate." (PMID 36077696, 2022). "We found that DUSP4 knockdown in four different BRAF-mutant melanoma cell lines induced significant proliferation arrest and apoptotic cell death as judged by dye dilution and Annexin V staining, respectively." (PMID 35580987, 2022). "Next, three MEK inhibitors, cobimetinib, trametinib, and binimetinib, were also approved for clinical use in advanced BRAF-positive melanoma." (PMID 36143375, 2022). "From these studies, it is evident that HO-1 plays an important role in melanoma disease progression and provides a promising target for overcoming BRAF inhibitor resistance going forward." (PMID 35326683, 2022). "Recent results of patients with advanced melanoma treated with first-line BRAF-MEK inhibitors in clinical trials showed 5-year survival in one-third of patients with a median overall survival (OS) of more than 2 years." (PMID 35703270, 2022). "The discovery of BRAF inhibitors such as vemurafenib and dabrafenib has improved the prognosis of melanoma patients." (PMID 35332658, 2022). "Upregulated MITF expression is related to inherent B-Raf inhibitor resistance, and MITF amplification is associated with BRAF-positive melanomas." (PMID 36143375, 2022). "The first clinically approved BRAF inhibitors, vemurafenib and dabrafenib, are effective in melanoma driven by V600E BRAF, but they are less effective in other contexts and can accelerate the progression of cutaneous squamous cell carcinomas." (PMID 35830914, 2022). "Several genes have been identified as genetically altered drivers of melanoma tumorigenesis, such as NRAS, CDNK2A, MITF, PTEN, KIT, GNAQ, GNA11 or CTNNB1, but most (60%) melanomas have BRAF gene mutations." (PMID 35326682, 2022). "In this paper, we further investigate this relationship by using a new computational model that copes with multiple cell states identified by single cell mRNA sequencing data in melanoma treated with BRAF/MEK inhibitors." (PMID 35494017, 2022). "Rather, survival outcomes of BRAF-mutant melanoma patients were impacted by the number of metastatic sites, presence of baseline brain metastasis, and poor baseline functional status." (PMID 35323326, 2022). "Following the positive results obtained through the combination of BRAF and MEK inhibitors in BRAF-mutant melanoma, the same combination was prospectively assessed in BRAF-mutant NSCLC." (PMID 36230797, 2022).
melanoma (continued). "Unlike Ca2+-ATPase, T-type VDCCs drive migration and invasion in BRAF mutant melanoma cells depending on Snail1 levels, suggesting therapeutic strategies by blocking T-type VDCCs to inhibit progression of melanoma." (PMID 35162934, 2022). "Ulixertinib (BVD-523) has shown early evidence of clinical activity in a phase I trial, that included both patients with NRAS-mutant melanoma and BRAF-mutant melanoma which progressed on or were refractory to BRAF and/or MEK inhibitors." (PMID 35053435, 2022). "The expression of lncRNA-RMEL3 is significantly increased in BRAF V600E mutant melanoma cells and can be regulated by BRAF and MEK inhibitors." (PMID 36601121, 2022). "Results from selected completed clinical trials investigating MEK inhibition as part of dual and triple therapy regimens in patients with KRAS-/BRAF-mutant solid tumors and melanoma." (PMID 35965494, 2022). "In M14 melanoma cells, the two inhibitors used as single agents targeting BRAF(V600E) differentially upregulated the expression of specific tyrosine kinases." (PMID 34958800, 2022). "Notably, many lines of evidence indicate that oncogenic BRAF can stimulate pro-survival autophagy in different tumor models and that the autophagic process can exert a cytoprotective function against Vemurafenib-induced cell death in BRAF-mutated tumors, including melanoma." (PMID 36009541, 2022). "In metastatic melanomas, CAFs resist the function of BRAF inhibitors via their crosstalk with tumor cells (vascular mimicry), the ECM, and endothelial cells (neovascularization)." (PMID 35326670, 2022). "High-level focal amplification of MITF has been found to mediate BRAF inhibitor resistance in melanoma." (PMID 35580987, 2022). "Vemurafenib-resistant melanoma cells often express alternatively spliced short BRAF V600E isoforms that lack the RAS-binding domain." (PMID 35883549, 2022). "A suitable cell model system to study BRAF-splicing mediated vemurafenib resistance are SK-MEL-239 melanoma cells that have acquired resistance." (PMID 35883549, 2022). "The evidence came from a histology-independent, flexible, early phase II “basket” study of vemurafenib in patients with non-melanoma cancers harboring BRAF." (PMID 35912223, 2022). "The receptor tyrosine kinase AXL has been found overexpressed in a wide range of cancers, including melanoma, and it was shown to mediate resistance to both target therapy (BRAF and MEK inhibitors) and immunotherapy." (PMID 35563772, 2022). "We have synthesized and evaluated a novel small molecule, indolium 1, which has activity against vemurafenib-resistant BRAF mutant melanoma." (PMID 35624662, 2022). "The CE-IVD labels for Idylla molecular assay are assigned only to specific tumor types for each assay-NSCLC for EGFR; CRC for KRAS, NRAS-BRAF and MSI, and melanoma for BRAF." (PMID 36293374, 2022). "In BRAF- and NRAS-mutated melanoma, tumor proliferation and cell survival are substantially driven by increased activation of the MAPK pathway." (PMID 35380338, 2022). "Previous studies have shown that patients with BRAF mutant melanoma regressed after conventional anti-BRAF and chloroquine combination therapy." (PMID 36034776, 2022). "PDGFRβ moves to melanoma cells via exosomal transport and activates the phosphatidylinositol-3-kinase (PI3K-AKT) signaling pathway, thereby reducing the susceptibility to BRAF inhibitors." (PMID 35974375, 2022). "In patients with BRAF-mutant melanoma, subgroup analysis of this population in KEYNOTE-054 at 3 years showed an HR for relapse or death of 0.51 for pembrolizumab versus placebo, the same as that reported with dabrafenib plus trametinib in COMBI-AD." (PMID 35538491, 2022). "LBH589 (panobinostat) is an HDACi, with broad specificity and a capacity to sensitize intrinsically resistant melanoma cells to BRAF inhibition." (PMID 35409020, 2022).
melanoma (continued). "In the past ten years, several breakthroughs have been developed in melanoma targeted therapeutics, including BRAF V600E-targeted inhibitors and ICIs." (PMID 36551302, 2022). "Analogously to METi and EGFRi, the EML4-ALK translocation-based cellular model H3211 was exposed to the ALK inhibitor crizotinib (ALKi) and the BRAF V600E-addicted melanoma cell line G361 to the BRAF inhibitor (BRAFi) vemurafenib." (PMID 36494469, 2022). "The introduction of immunotherapy with Immune checkpoint Inhibitors (ICI) and of targeted therapy with BRAF and MEK inhibitors for BRAF mutated melanoma, has greatly improved the clinical outcome of these patients." (PMID 36438490, 2022). "Recently, two unique paradox inhibitors, PLX8394 and PLX7904, were described in colon adenocarcinoma and resistant melanoma xenografts due to BRAF amplification." (PMID 35954441, 2022). "Our data show that both MITF-high and MITF-low BRAF-mutant melanoma cells can acquire MAPKi resistance and that their response to DUSP4 depletion remains unchanged despite changes in MITF levels during the acquisition of drug resistance." (PMID 35580987, 2022). "Approximately 90% BRAF mutations, 45% PTEN phosphatase-related gene depletion and 45% AKT amplification are found in melanomas." (PMID 36539659, 2022). "BRAF and NRAS are two major genes often mutated in human melanoma and are associated with melanoma initiation and progression." (PMID 36291794, 2022). "We detected mutations in six genes in the EVs (BRAF, NRAS, CDKN2A, STK19, PPP6C, and RAC), and at least one mutation was detected in all melanoma EV samples." (PMID 36531960, 2022). "A rare histological variant is the desmoplastic melanoma arising on chronic sun-damaged skin and is uniquely characterized by NFKBIE (NFKB inhibitor epsilon) promoter mutation, rare types of BRAF mutation and high tumor mutational burden (TMB)." (PMID 35628196, 2022). "In the survival analysis, the BRAF WT primary melanoma population was dichotomized into patients with high or low miR-125b, miR-200c or miR-205 expression depending on their corresponding median values." (PMID 35326682, 2022). "They employed a chemoproteomics approach to study the differences in kinome reprogramming in the M14 melanoma cell line between two FDA-approved BRAF inhibitors, Dabrafenib and Vemurafenib." (PMID 34958800, 2022). "To do this, we performed a focused siRNA-based screen in BRAFV600E melanoma cells targeting either direct or indirect negative regulators of the BRAF-MEK-ERK pathway, where the effects of knockdown on cell growth were assessed over time." (PMID 35580987, 2022). "On the other hand, melanoma invasion in the vem + pic group was effectively suppressed (40.1 ± 9.6 μm), suggesting the synergistic effect of BRAF/PI3K combined inhibition." (PMID 36026581, 2022). "Still other gene signatures have been reported to predict the sensitivity, as well as eventual resistance, of melanoma patients to BRAF inhibitors." (PMID 35044091, 2022). "IGF1R is stabilized in melanoma cells by the activation of the BRAF oncogene, PTEN suppressor, or by contact with cancer-associated fibroblasts, which leads to its increased expression." (PMID 35565444, 2022). "ZIC5 knockdown induced apoptosis in melanoma cells and synergistically enhanced apoptosis when using a BRAF inhibitor." (PMID 36282887, 2022). "Additional trials studied the ideal sequencing of immune and targeted therapies for advanced BRAF mutated melanoma and have shown superiority in survival and response rates when ICI are used as first-line over BRAF/MEK targeted therapies." (PMID 36358601, 2022). "TCGA melanoma samples were dichotomized into high and low BRAF score groups using the median BRAF score as the threshold." (PMID 35044091, 2022). "MEK inhibitor monotherapy has activity in BRAF V600 wild-type, NRAS Q61R/K/L mutant melanoma and BRAF V600 wild-type/NRAS Q61R/K/L wild-type melanoma but is associated with considerable treatment-limiting skin toxicity." (PMID 36058945, 2022).